NEDD4L (NEDD4 like E3 ubiquitin protein ligase)
Diseases named in the same sentence as NEDD4L in open-access papers (continued):
Sharing a sentence is not in itself a finding about the gene and the disease.
esophageal cancer (5 papers, 2021 to 2024). A primary or metastatic malignant neoplasm involving the esophagus. "This study suggests that NEDD4L may be the early diagnostic molecular biomarker and potential therapeutic target for esophageal carcinoma." (PMID 38831335, 2024). "A bioinformatics analysis revealed that NEDD4L was downregulated in esophageal cancer patients and might be associated with esophageal cancer prognosis." (PMID 34869021, 2021). "The intersection was taken to obtain 33 NEDD4L-specific ubiquitination degraded proteins in esophageal carcinoma." (PMID 38831335, 2024). "Our results suggested that, high NEDD4L expression markedly prolonged the survival of mice, while after reversing ITGB4 expression, NEDD4L lost its function in extending the survival of mice with esophageal carcinoma lung metastasis." (PMID 38831335, 2024). "From the perspective of function, cloning and Transwell assays also confirmed that the HECT domain of NEDD4L suppressed the proliferation and migration of esophageal carcinoma cell lines ECA109 and TE13." (PMID 38831335, 2024). "Based on GEO database data, it was discovered in this study that, the expression of NEDD4L in esophageal carcinoma was apparently lower than that in atypical hyperplastic esophageal tissue and esophageal squamous epithelium." (PMID 38831335, 2024). "At the same time, the expression of NEDD4L was negatively correlated with ITGB4 expression in esophageal carcinoma." (PMID 38831335, 2024). "Our findings in esophageal carcinoma are consistent with conclusions made in other tumor research, suggesting that the variation of NEDD4L in tumor affects the progression of esophageal carcinoma." (PMID 38831335, 2024). "In experiments in vivo and in vitro, NEDD4L suppressed the growth and metastasis of esophageal carcinoma." (PMID 38831335, 2024). "Kaplan-Meier method was used for survival analysis of 141 esophageal carcinoma patients, the results suggested that patients with high NEDD4L expression had significantly longer progression-free survival than those with low expression." (PMID 38831335, 2024). "According to our results in this study, NEDD4L exerts the role of E3 ubiquitin ligase activity to suppress the malignant phenotype of esophageal carcinoma." (PMID 38831335, 2024). "To further explore the antitumor role of NEDD4L in vivo, we constructed the esophageal carcinoma xenograft model." (PMID 38831335, 2024). "At the end of the mouse model, data verified that the tumor weight of mice inoculated with NEDD4LHigh ECA109 cells apparently decreased, while NEDD4L inhibited 60.9% of esophageal carcinoma growth." (PMID 38831335, 2024). "To verify the impact of NEDD4L on the malignant phenotype of esophageal carcinoma, we constructed the NEDD4L high-expression TE13 and ECA109 cell lines for cloning and Transwell assays." (PMID 38831335, 2024). "Experiments in vivo and in vitro also verified that NEDD4L suppressed the growth and metastasis of esophageal carcinoma." (PMID 38831335, 2024). "The results suggested that, the expression of NEDD4L in normal esophagus was apparently higher than that in esophageal carcinoma tissue (GSE46452)." (PMID 38831335, 2024). "In experiments in vivo and in vitro, NEDD4L suppresses the proliferation and migration of esophageal carcinoma cells." (PMID 38831335, 2024). "While after restoring ITGB4 expression, NEDD4L lost its suppression on the growth of esophageal carcinoma." (PMID 38831335, 2024). "To explore the role of NEDD4L-regulated ubiquitination modification in suppressing the malignant phenotype of esophageal carcinoma, we screened the NEDD4L ubiquitination-degraded protein." (PMID 38831335, 2024). "The mRNA levels of NEDD4L in adjacent normal control (N) and esophageal cancer (T) tissues were measured." (PMID 35593463, 2022). "Results showed that NEDD4L was significantly down-regulated in esophageal cancer tissue compared with that in adjacent normal control tissue from both TCGA RNA-seq data and clinical data." (PMID 35593463, 2022).
esophageal cancer (continued). "Besides, patients with high expression of NEDD4L in esophageal carcinoma tissue had longer progression-free survival than those with low expression." (PMID 38831335, 2024). "Furthermore, as revealed by in vivo and in vitro growth and metastasis models, NEDD4L suppressed the growth and metastasis of esophageal carcinoma." (PMID 38831335, 2024). "Moreover, patients with high expression of NEDD4L in esophageal carcinoma tissue have longer progression-free survival than those with low expression." (PMID 38831335, 2024). "To evaluate the role of NEDD4L expression on the prognosis of esophageal carcinoma patients, we downloaded esophageal carcinoma and para-carcinoma expression data from GEO database to explore the expression of NEDD4L in cancer and para-carcinoma tissue samples." (PMID 38831335, 2024). "In the subcutaneous esophageal carcinoma tumor bearing model and 96 pairs of surgical tissue samples from esophageal carcinoma patients, immunohistochemistry analysis further verified that NEDD4L was negatively correlated with ITGB4 expression." (PMID 38831335, 2024). "Based on public esophageal carcinoma database and clinical sample data, it was discovered in this study that the expression of NEDD4L in esophageal carcinoma was apparently lower than that in atypical hyperplastic esophageal tissue and esophageal squamous epithelium." (PMID 38831335, 2024). "Moreover, with the deterioration of malignancy grade of esophageal carcinoma, the patient survival markedly decreased, while high NEDD4L expression extended the patient survival." (PMID 38831335, 2024). "Additionally, patients with high expression of NEDD4L in esophageal carcinoma tissue had longer progression-free survival than those with low expression." (PMID 38831335, 2024). "Moreover, we observed the effect of NEDD4L-mediated ubiquitination degradation of ITGB4 on the survival of mice by suppressing the metastasis of esophageal carcinoma." (PMID 38831335, 2024). "Finally, the protein ITGB4, which was related to esophageal carcinoma progression and could be degraded by NEDD4L through ubiquitination, was screened." (PMID 38831335, 2024). "However, the anti-tumor role of NEDD4L in esophageal carcinoma, and the potential specific recognition substrate remain unclear." (PMID 38831335, 2024). "We collected 117 esophageal carcinoma and para-carcinoma tissue samples from Jiangsu University Affiliated People’s Hospital and confirmed through Western blot and immunohistochemistry that, the expression of NEDD4L in ESCC tissue was markedly lower than that in para-carcinoma tissues." (PMID 38831335, 2024). "However, the anti-tumor role of NEDD4L in esophageal carcinoma and the possible specifically recognized substrate remain unclear." (PMID 38831335, 2024). "Subsequently, based on the bioinformatics platform UbiBrowser, the esophageal carcinoma TCGA database and GEO database (GSE53625), we screened the ITGB4 protein, which was related to the progression of esophageal carcinoma, and could be degraded by NEDD4L-mediated ubiquitination." (PMID 38831335, 2024). "Similarly, the esophageal carcinoma metastasis model also suggested that, after restoring ITGB4 expression, NEDD4L lost its suppression on the metastasis of esophageal carcinoma." (PMID 38831335, 2024). "In terms of the mechanism, the HECT domain of NEDD4L specifically bound to the Galx-β domain of ITGB4, which modified the K915 site of ITGB4 in an ubiquitination manner, and promoted the ubiquitination degradation of ITGB4, thus suppressing the malignant phenotype of esophageal carcinoma." (PMID 38831335, 2024). "Mechanically, the HECT domain of NEDD4L specifically bound to the Galx-β domain of ITGB4, which modified the K915 site of ITGB4 in an ubiquitination manner, and promoted the ubiquitination degradation of ITGB4, thus suppressing the malignant phenotype of esophageal carcinoma." (PMID 38831335, 2024).
esophageal cancer (continued). "Mechanically, the HECT domain of NEDD4L specifically binds to the Galx-β domain of ITGB4, which modifies the K915 site of ITGB4 through ubiquitination, and promotes the ubiquitination degradation of ITGB4, thus suppressing the malignant phenotype of esophageal carcinoma." (PMID 38831335, 2024).
malignant glioma (5 papers, 2013 to 2022). A grade III or grade IV glioma arising from the central nervous system. "The inhibition of NEDD4L has been reported to be related to the aggressive progression and dismal prognosis of malignant glioma." (PMID 36052751, 2022). "The expression of NEDD4L was in negatively correlated with the pathological grade of malignant glioma, and low expression of NEDD4L indicated poor outcomes." (PMID 34869021, 2021). "Moreover, NEDD4L mediates the ubiquitination of the tumor oncogene sphingosine kinase 2 (SphK2) and thus suppresses the development of malignant glioma." (PMID 34869021, 2021).
Parkinson disease (5 papers, 2013 to 2023). A progressive degenerative disorder of the central nervous system characterized by loss of dopamine producing neurons in the substantia nigra and the presence of Lewy bodies in the substantia nigra and locus coeruleus. "In Parkinson’s disease (PD) model, NEDD4L promoted the ubiquitination of glutamate transporters in vitro and in vivo." (PMID 32140098, 2020). "We first tested the accuracy of two machine learning-built models and finally chose to use the random forest to obtain five Parkinson’s disease FRHGs (CISD1, SIRT2, NUPR1, ADAM23 and NEDD4L)." (PMID 38127902, 2023). "The top 5 genes were extracted as FRHGs in Parkinson’s disease (CISD1, SIRT2, NUPR1, ADAM23 and NEDD4L)." (PMID 38127902, 2023). "The Yellow module yielded three FRGs in Parkinson’s disease (CISD1, ADAM23 and NEDD4L)." (PMID 38127902, 2023).
Sepsis (5 papers, 2020 to 2026). Sepsis is defined as life-threatening organ dysfunction caused by a dysregulated host response to infection. "Although the clinical significance of NEDD4L in sepsis appears promising, our study has a few limitations." (PMID 36291692, 2022). "Combined our findings with the function of NEDD4L in various organs, NEDD4L may be involved in multi-organ failure due to sepsis, but further research is needed to validate this." (PMID 36291692, 2022). "Lastly, NEDD4L was identified from the 14 FAGs as a potential hub gene for sepsis prediction." (PMID 36291692, 2022). "Single-cell RNA sequencing of a sepsis-induced ALI mouse model and in vitro assays revealed marked upregulation of NEDD4L in endothelial cells under ALI-related pathological stimuli (LPS, TNFα, H2O2)." (PMID 41943017, 2026). "Despite the identification of several ferroptosis-related genes, such as NEDD4L and NCF2, through transcriptomic analyses and machine learning models, validation in independent human sepsis cohorts remains limited." (PMID 41250137, 2025). "For example, melatonin attenuates sepsis‐induced lung injury by activating the serum and glucocorticoid regulated kinase 1 (SGK1)–NEDD4L pathway." (PMID 35355403, 2022).
type 2 diabetes (5 papers, 2013 to 2026). "NEDD4L is associated with type 2 diabetes and cardiovascular continuous complications represented by ischemic heart disease (IHD)." (PMID 30521536, 2018).
viral infection (5 papers, 2010 to 2021). "Deficiency of Nedd4l significantly impairs type I interferon and proinflammatory cytokine production induced by virus infection both in vitro and in vivo." (PMID 33608556, 2021). "Interaction between endogenous TRAF3 and Nedd4l was also detectable in macrophages following virus infection." (PMID 33608556, 2021).
breast tumor (4 papers, 2020 to 2024). "The miR-106b-25 cluster through the direct repression of NEDD4L mediated breast tumor initiation by the activation of NOTCH1 signaling." (PMID 34809620, 2021). "Clinically, we observed that the expression of Nedd4l was reduced in breast tumors compared to the adjacent normal tissues, meanwhile, the expression of Nedd4l was negatively correlated with CTR1 expression." (PMID 34278744, 2021).
esophageal squamous cell carcinoma (4 papers, 2022 to 2025). Esophageal squamous cell carcinoma (ESCC) is a type of esophageal carcinoma (EC) that can affect any part of the esophagus, but is usually located in the upper or middle third. "Studies have shown that NEDD4L inhibits esophageal squamous cell carcinoma by inducing MYC ubiquitination and decreasing SLC1A5 expression." (PMID 41561975, 2025). "Here, we reported that NEDD4L, an E3 ubiquitin ligases, inhibited esophageal squamous cell carcinoma (ESCC) tumor growth and facilitated ferroptosis by ubiquitination of xCT." (PMID 39557844, 2024).
kidney damage (4 papers, 2020 to 2025). "This supports our findings that loss of NEDD4L may contribute to the development of nephropathy, with the potential for its expression levels to be utilized as a biomarker for early stage disease." (PMID 31802037, 2020).
lymph node metastasis (4 papers, 2019 to 2024). "Down-regulated NEDD4L expression is negatively associated with histological grade, lymph node metastasis, and pathological stage in NSCLC." (PMID 35646490, 2022). "In addition, further analysis confirmed that low expression of NEDD4L (p < 0.05), invasion (p < 0.05) and lymph node metastasis (p < 0.05) are risk factors for poor prognosis." (PMID 39557844, 2024). "Contrarily, the NEDD4L and HIF-1α expression did not correlate with gender, age, lymph node metastasis and tumor location." (PMID 31673244, 2019).
multiple myeloma (4 papers, 2022 to 2024). "NEDD4L can also bind to the 19S proteasome, inhibiting its hydrolytic function and enhancing autophagy and sensitivity to bortezomib in multiple myeloma cells." (PMID 38027016, 2023). "NEDD4L can also exert pro-autophagic and tumor suppressor activities in multiple myeloma and cervical cancer cells and increases the drug sensitivity in multiple myeloma." (PMID 36918822, 2023). "NEDD4L exerts a tumor suppressive role and is correlated with poor prognoses in cancer cells where its expression is low, such as multiple myeloma (MM), non-small cell lung carcinoma, malignant gliomas, and gastric cancer." (PMID 36918822, 2023). "Our finding that low expression of NEDD4L attenuated the anti-MM activity of Bor both in vitro and in vivo provides a biological rationale for the use of a NEDD4L activator in combination with Bor as a novel therapeutic strategy for the treatment of multiple myeloma." (PMID 35236820, 2022).
Obesity (4 papers, 2009 to 2025). Accumulation of substantial excess body fat. "In conclusion, we analyzed three common variants in NEDD4L, namely rs2288774, rs3865418 and rs4149601, for association with overweight/obesity and 11 related phenotypes." (PMID 23549273, 2013). "No other studies and replications are available on the issue of whether NEDD4L genetic variation is a contributing factor to the risk of obesity." (PMID 23549273, 2013). "Together with results from the recent studies, these consistent findings warrant research into a potential role for NEDD4L modulators in the prevention and treatment of human obesity." (PMID 23549273, 2013). "Recently, a common polymorphism located at exon 1 (rs4149601) of the NEDD4L gene was shown to be associated with obesity in Kazakh and to not be associated in the same group for another common polymorphism located at intron 12 (rs3865418)." (PMID 23549273, 2013).
renal cell carcinoma (4 papers, 2021 to 2024). "Our study offers insight into NEDD4L as a potential future therapeutic target for renal cell carcinoma or as a novel prognostic biomarker." (PMID 39596003, 2024). "Immunohistochemical results showed that the expression level of NEDD4L in renal cell carcinoma was significantly decreased than that in normal kindey." (PMID 34458018, 2021). "RAC2 is the first identified target of NEDD4L in renal cell carcinoma." (PMID 39596003, 2024).
Stroke (4 papers, 2009 to 2025). Sudden impairment of blood flow to a part of the brain due to occlusion or rupture of an artery to the brain. "Therefore, the primary aim of this research is to investigate the regulatory mechanism underlying NEDD4L in stroke-induced ferroptosis." (PMID 38302612, 2024). "By controlling TFRC levels, NEDD4L can reduce iron uptake and suppress iron-dependent oxidative cell death pathways like ferroptosis after stroke." (PMID 38302612, 2024). "Our previous work revealed the E3 ubiquitin ligase NEDD4L as a novel regulator of ferroptosis in stroke models." (PMID 38302612, 2024). "In mouse stroke models, we found METTL3 overexpression increased NEDD4L levels, enhanced TFRC ubiquitination and degradation, limited iron accumulation, and reduced oxidative damage and ferroptotic cell death, resulting in smaller infarct sizes and improved neurological function." (PMID 38302612, 2024). "As NEDD4L suppresses ferroptosis and iron-mediated neuronal death after stroke by ubiquitinating the iron transporter TFRC, we explored whether boosting METTL3 could protect the brain against ischemia through modulating the NEDD4L-TFRC pathway." (PMID 38302612, 2024).
Arrhythmia (3 papers, 2020 to 2025). Any cardiac rhythm other than the normal sinus rhythm. "Studies indicated that reduced NEDD4L function results in serious heart arrhythmia via modifications of cardiac ion-channels after transcription." (PMID 33110392, 2020). "However, further study is needed to clarify which substrate ubiquitinated by NEDD4L is involved in arrhythmia." (PMID 33110392, 2020).
cervical cancer (3 papers, 2023 to 2024). A primary or metastatic malignant neoplasm involving the cervix. "The autophagic activity of NEDD4L was further supported by another study that indicated NEDD4L mediates ER stress-induced autophagy as well as autophagy induced by both basal and nutrient starvation conditions in cultured cervical cancer cells and in the mouse." (PMID 36918822, 2023).
depression (3 papers, 2016 to 2023). "Conversely, knock down of Nedd4l in the mPFC decreased the degradation of NRG1 and rescued the behavioural changes in CSDS-induced depression-like behaviours, which strongly support that the expression of Nedd4l in the mPFC neurons is required for NRG1 deficiency-mediated susceptibility to stress." (PMID 32703967, 2020). "Nedd4l-mediated downregulation of NRG1 in the medial prefrontal cortex induced depression-like phenotypes mice in chronic social defeat stress." (PMID 37061663, 2023). "Overall, we currently explained a possible mechanism by which Nedd4l mediates depression-like behaviours by inducing NRG1 degradation following stress." (PMID 32703967, 2020). "To further confirm that Nedd4l is required for NRG1 degradation in depression, we downregulated Nedd4l via the Si-Nedd4l virus in Dex-treated primary cortical neurons." (PMID 32703967, 2020). "Our data strongly indicate that the Nedd4l-mediated downregulation of NRG1 acts as a critical role in depression-like phenotypes of mice in CSDS." (PMID 32703967, 2020). "To determine whether Nedd4l in the mPFC neurons is required for susceptibility to stress, we firstly evaluated whether Nedd4l knock down could rescue CSDS-induced depression-like behaviours." (PMID 32703967, 2020). "We here assessed the regulation of NRG1 by the E3 ubiquitin ligase Nedd4l (neural precursor cell expressed developmentally downregulated 4-like) and investigated whether NRG1 changes in the mPFC might lead to vulnerability to depression-like behaviours." (PMID 32703967, 2020). "Therefore, we speculated that Nedd4l downregulates NRG1 protein level through the ubiquitin-mediated proteolysis system in SS mice subjected to CSDS, finally leading to depression-like phenotypes." (PMID 32703967, 2020).